KIF2C (kinesin family member 2C)
Diseases named in the same sentence as KIF2C in open-access papers (continued):
Sharing a sentence is not in itself a finding about the gene and the disease.
gastric cancer (17 papers, 2007 to 2024). A primary or metastatic malignant neoplasm involving the stomach. "It has been reported that KIF2C can stimulate the proliferation and migration of gastric cancer cells as well as non-small cell lung cancer cells." (PMID 37717078, 2023). "KIF2C has also been identified as a putative oncogene that is highly expressed in breast cancer, gastric cancer, colorectal cancer, glioma, and non-small cell lung cancer." (PMID 32748349, 2021). "Moreover, knockdown of KIF2C reduced cell proliferation of gastric cancer cells (GES-1, AGS, MKN-45, NCI-N87, and SNU-1)." (PMID 38344808, 2024). "KIF2C has been reported to be involved in the proliferation and migration of gastric cancer cells and non-small cell lung cancer cells, however, the precise role and mechanism remain unclear." (PMID 32748349, 2021). "The gene expression of KIF2C was reported to be significantly higher in gastric cancer tissues compared to its expression in nonmalignant tissues." (PMID 38344808, 2024). "In vitro studies showed that overexpression of KIF2C enhanced cell migration and proliferation with a correlation between the high levels of KIF2C and multiple proliferation genes (CCN2A, CCNB1, CCNB2, CCNE1, CDK1 and CDK2) in gastric cancer tissues." (PMID 38344808, 2024). "Previous study showed that gastric cancer cells transfected with KIF-2C, but not controls, exhibited increased proliferation, migration, and decreased anoikis." (PMID 27563815, 2016).
lung cancer (16 papers, 2015 to 2025). A malignant neoplasm involving the lung. "Survival analysis revealed that overexpression of CDK1, PLK1, AURKA, KIFC1, and KIF2C was associated with a statistically significant unfavorable overall survival in patients with lung cancer." (PMID 40232858, 2025). "For instance, KIF2C is crucial for chromosome segregation and spindle assembly during mitosis, and its overexpression is associated with poor prognosis in several cancers, including breast and lung cancers." (PMID 39201599, 2024). "In this paper, we presented experimental proof that, in comparison to BEAS-2B, KIF2C was significantly expressed in various kinds of lung cancer cell lines such as LUAD and LUSC." (PMID 37142638, 2023). "Recent studies highlighted the role of KIF2C as an oncogene, and correlated it with the prognosis of lung cancer." (PMID 31991631, 2020). "This suggests that KIF2C in lung cancer may exert its oncogenic effects and influence patient prognosis through pathways similar to those observed in HCC." (PMID 41333555, 2025). "Compared to normal tissues, ASPM and KIF2C expressions were significantly elevated in lung cancer tissues within three datasets (Hou Lung, Selamat Lung, and Okayama Lung) and five datasets (Hou Lung, Landi Lung, Okayama Lung, Stearman Lung, and Su Lung), respectively." (PMID 33187219, 2020). "The roles of KIF4A, KIF11 and KIF2C in lung cancer have been already reported, while the involvement of KIF20A in LUAD remains largely unknown." (PMID 30105795, 2018). "In addition to our findings on LMO1, we identified five genes (GNG4, NCAPG, SPC25, ASPM and KIF2C) that are expressed at higher levels in lung tumors relative to NATs and are significantly correlated with poor survival of lung cancer patients, suggesting possible oncogenic functions in lung cancer." (PMID 30038707, 2018). "CENPF (Centromere protein F) is a gene related to chromosome segregation during mitosis that reduces overall survival in lung cancer and is a hub gene (AURKB, BUB1B, KIF2C, HMMR, CENPF, and CENPU) overexpressed in cancer patients." (PMID 36661515, 2023). "In the context of lung cancer, although no studies have directly confirmed a direct interaction between KIF2C and CDK1/CCNB1, research has identified a significant positive correlation in their expression levels." (PMID 41333555, 2025).
non-small cell lung carcinoma (12 papers, 2017 to 2023). A group of at least three distinct histological types of lung cancer, including non-small cell squamous cell carcinoma, adenocarcinoma, and large cell carcinoma. "There has been extensive study of the involvement of KIF2C in cancer progression and development, including studies of non-small cell lung cancer, endometrial carcinoma, glioma, and hepatocellular carcinoma." (PMID 37717078, 2023). "This study aimed to explore how kinesin family member 2C (KIF2C) influences the progression of non-small cell lung cancer (NSCLC)." (PMID 37142638, 2023). "KIF2C also exerts an oncogenic role and is negatively regulated by miR-325-3p in non-small-cell lung cancer (NSCLC)." (PMID 34650608, 2021). "Elevated level of KIF2C was found in non-small cell lung cancer cells, which promotes cancer cell migration and could be suppressed by targeting the RAS-RAF-MEK1 pathway." (PMID 28754978, 2017). "KIF2C is an important regulator of chromosome segregation, bipolar spindle formation, and microtubule depolymerization during mitosis, and it may be related with poor prognosis in non-small cell lung cancer." (PMID 34568334, 2021).
endometrial cancer (11 papers, 2021 to 2024). Primary or metastatic malignant neoplasm involving the endometrium (mucous membrane that lines the endometrial cavity). "Furthermore, many studies have reported that KIF2C is upregulated in colorectal, breast, and endometrial cancer tissues and is greatly linked to immune infiltration, lymph node metastasis, and OS in cancer patients." (PMID 36072970, 2022). "KIF2C was found to be highly upregulated among 344 other genes differentially expressed in endometrial cancer." (PMID 38344808, 2024). "Researchers in endometrial cancer have found that the knockout of KIF2C can inhibit the apoptosis of CD8+T cells and ki-67 expression." (PMID 36900292, 2023). "Knockdown of KIF2C in mouse inhibited the apoptosis of CD8+ T cell and affected the immune cells infiltration that was associated with endometrial cancer." (PMID 35328051, 2022). "Interestingly, on a functional level, KIF2C was shown to stimulate the proliferation, migration and invasion of two endometrial cancer cell lines (Ishikawa and RL95–2)." (PMID 38344808, 2024). "Notably, KIF2C has been revealed as a prognostic biomarker in endometrial cancer and correlated with the infiltration level of CD8+ T cells." (PMID 36032071, 2022). "study found that knocking down KIF2C decreased CD8+ T cell apoptosis, which was further inhibited when paired with anti-PD1 in endometrial cancer." (PMID 35720323, 2022). "In contrast, the negative effect of KIF2C on immune cells infiltration has been observed in endometrial cancer." (PMID 37016301, 2023).
bladder cancer (10 papers, 2020 to 2025). "KIF2C, part of the kinesin superfamily, is implicated in various cancers, with overexpression observed in breast, lung, and bladder cancers." (PMID 39859485, 2025). "They found that the overexpression of KIF2C was associated with increased invasion, migration and proliferation in the bladder cancer cell lines T24 and UM-UC-3." (PMID 38344808, 2024). "We considered KIF2C as a stemness‐related gene based on studies in breast, kidney and bladder cancer." (PMID 39840448, 2025). "The downregulated miR-548x expression or upregulated KIF2C expression could rescue the invasive ability of bladder cancer cells, following circRGNEG silencing." (PMID 40345591, 2025). "Because KIF2C is involved in the regulation of tumor development, proliferation, and metastasis, it has been considered as a candidate promoting factor for breast cancer, liver cancer, lung cancer, bladder cancer, colon cancer, and other cancers." (PMID 35153749, 2021). "Finally, a study indicated KIF2C as a key hub gene in bladder cancer." (PMID 38344808, 2024). "Similarly, overexpression of KIF2C promotes bladder cancer progression." (PMID 34650608, 2021). "Several single reports or dataset analyses deal with the expression of KIF2C in cervical cancer, nasopharyngeal carcinoma (NPC), laryngeal squamous cell carcinoma (LSCC), laryngeal squamous-cell cancer and bladder cancer." (PMID 38344808, 2024).
lymph node metastasis (10 papers, 2007 to 2024). "High KIF2C expression was associated with age, pathological stage, lymph node metastases, prostate-specific antigen (PSA), and Gleason score and significantly predicted an unfavorable prognosis in PCa patients." (PMID 35720323, 2022). "Elevated expression of KIF2C is associated with poorer differentiation status and lymph node metastasis in NSCLC." (PMID 34307447, 2021). "In our study, we also showed that high expression of KIF2C was associated with an increase in tumor stage, Gleason score, PSA score, lymph node metastasis, and distant metastasis in PCa." (PMID 35720323, 2022). "Furthermore, overexpression of KIF2C resulted in significantly higher lymphatic invasion, lymph node metastasis, serosal invasion and a reduced patient survival." (PMID 38344808, 2024). "The first studies were conducted almost two decades ago, where Nishidate and colleagues identified KIF2C as one of 34 genes that were expressed differentially in breast tumors with lymph node metastasis compared to tumors without metastasis." (PMID 38344808, 2024).
cervical carcinoma (9 papers, 2016 to 2024). A carcinoma arising from either the exocervical squamous epithelium or the endocervical glandular epithelium. "In cervical cancer, the authors showed that KIF2C mutation is strongly associated with the survival rate, and that KIF2C expression was significantly upregulated in cervical cancer tissues and cervical cancer cells." (PMID 38344808, 2024). "KIF2C mutation is strongly associated with the survival rate of cervical cancer, and KIF2C expression was significantly upregulated in cervical cancer tissues and cervical cancer cells." (PMID 35153749, 2021). "KIF2C resulted in tumorigenesis due to abnormal cell cycle progression and metastasis in cervical cancer." (PMID 36900109, 2023). "To explore the possibility of KIF2C as a therapeutic target of cervical cancer, we first detected its expression in human tissues." (PMID 35153749, 2021). "In summary, our study provided a relatively comprehensive description of KIF2C as an oncogenic gene and suggested KIF2C as a therapeutic target for cervical cancer." (PMID 35153749, 2021). "Because we found that KIF2C was clinically relevant in cervical cancer in the discussion earlier, we examined the KIF2C expression in various cervical cancer and normal cell lines, including C33a, HeLa, SiHa, Caski, and HCerEpic cell lines." (PMID 35153749, 2021). "To further probe the role of KIF2C in cervical cancer cells, we transfected the KIF2C overexpression plasmid into the Caski cell line." (PMID 35153749, 2021). "Through in vivo experiments, KIF2C was found to play an important role in the development of cervical cancer." (PMID 35153749, 2021). "To further investigate the role of KIF2C in cervical cancer, we established the stable KIF2C knockdown cell lines using the short hairpin RNA lentiviral system." (PMID 35153749, 2021). "We also found a significant correlation between KIF2C and clinicopathological characteristics, particularly in cervical cancer, which is the most common gynecological malignancy and is the second leading cause of cancer-related deaths among women worldwide." (PMID 35153749, 2021). "By the same token, a transwell assay was performed to examine cell migration and invasion ability, and the results demonstrated that KIF2C overexpression can remarkably improve the migration and invasion ability of cervical cancer cells." (PMID 35153749, 2021). "At the same time, immunohistochemical results in public datasets also showed that KIF2C was only highly expressed in cervical cancer tissue." (PMID 35153749, 2021). "To explore the role of KIF2C in cervical cancer cells, we examined the cell viability using CCK-8 assay and clone formation assay in SiHa or C33a cells." (PMID 35153749, 2021). "This suggested a latent relationship for KIF2C with the proliferation of cervical cancer." (PMID 35153749, 2021). "Hence, we experimentally confirm that KIF2C expression was increased in cervical cancer tissues and cervical cancer cells." (PMID 35153749, 2021).
cervical carcinoma (continued). "Relationship between KIF2C and clinicopathological characteristics in cervical cancer patients." (PMID 35153749, 2021). "Moreover, KIF2C promoted cervical cancer cells proliferation, invasion, and migration in vitro and as well increased tumor growth in vivo." (PMID 35153749, 2021). "Interestingly, we identified KIF2C that has a significant value for the research in cervical cancer." (PMID 35153749, 2021). "Downregulation of the KIF2C expression could significantly inhibit the biological functions of cervical cancer cell lines both in vitro and in vivo." (PMID 35153749, 2021). "This prompted us to investigate further the biological function of KIF2C in cervical cancer, which might provide new druggable targets and novel possibilities for cervical cancer therapy." (PMID 35153749, 2021). "Immunohistochemical staining showed that KIF2C was highly expressed in cervical cancer tissues." (PMID 35153749, 2021). "Moreover, KIF2C was shown to regulate cell polarity, protrusion formation, centrosome reorientation during migration and the FA turnover by regulating the plus-tip dynamics in human cervical cancer cells and retinal pigment epithelial cells." (PMID 38344808, 2024). "The study suggested that KIF2C might be a novel therapeutic target for cervical cancer." (PMID 38344808, 2024). "Therefore, we assumed that KIF2C might be involved in the occurrence and development of cervical carcinoma." (PMID 35153749, 2021). "The results showed that KIF2C expression was correlated with the type of cervical cancer (p < 0.05), whereas it was not directly correlated with age, tumor–nodes–metastases stage, 2018 International Federation of Gynecology and Obstetrics stage, lymphatic metastasis, and distant metastasis." (PMID 35153749, 2021). "Findings showed that KIF2C was upregulated in cervical cancer tissues compared with normal tissues." (PMID 35153749, 2021). "In the present paper we identified six putative biomarkers (AURKA, DTL, HMGB3, KIF2C, NEK2, and RFC4) which should be further tested to separate indolent HPV related cervical infections from progressive CIN III lesions and for early diagnosis of cervical cancer." (PMID 26701206, 2016).
liver cancer (9 papers, 2020 to 2025). An epithelial or non-epithelial malignant neoplasm that arises from the liver. "We verified the expression level of KIF2C in liver cancer tissues by immunohistochemistry, and the results were consistent with the database." (PMID 35685442, 2022). "Among them, MCODE 1 mainly comprised the mutations of CDK1, KIF2C, KIF18A, CENPA, and PLK1, which take part in the tumorigenesis and progression of liver cancer." (PMID 34414037, 2021). "qPCR validation in normal liver and HCC tissues showed that CCNA2, CSRP2, ILF2, KIF2C, RACGAP1, and VARS were significantly upregulated in the HCC group (all p-values < 0.0001), providing more evidence for their role in liver cancer progression and potential as HCC biomarkers." (PMID 41323394, 2025).
lung adenocarcinoma (7 papers, 2013 to 2024). A carcinoma that arises from the lung and is characterized by the presence of malignant glandular epithelial cells. "In lung adenocarcinoma, KIF2C is highly expressed and is associated with the recurrence and stage of lung adenocarcinoma." (PMID 31285741, 2019). "At the same time, KIF2C mRNA levels have been analyzed in human lung adenocarcinomas (LUAD), lung squamous cell carcinomas(LUSC), and normal lung tissue in the Cancer Genome Atlas (TCGA) dataset." (PMID 37142638, 2023). "KIF2C overexpression was revealed to be correlated with reduced immune infiltration in lung adenocarcinoma." (PMID 34650608, 2021). "The purpose of this study was to determine KIF2C expression levels in human lung epithelial cells BEAS-2B and different types of NSCLC cell lines, such as mouse lung adenocarcinoma LLC, human lung adenocarcinoma cells A549, PC-9, SHP-77, A549-DDP, NCI-H1703, through qRT-PCR." (PMID 37142638, 2023).
ovarian carcinoma (5 papers, 2014 to 2024). A malignant neoplasm originating from the surface ovarian epithelium. "In an analysis of a dataset of 396 OC samples and 54 controls, upregulated KIF2C was detected as one of 12 hub genes for OC progression in a protein interaction network, and its expression was negatively associated with poor OS of patients with epithelial ovarian cancer." (PMID 38344808, 2024). "Intriguingly, the authors showed that KIF2C was downregulated in the platinum resistant ovarian cancer cell line A2780." (PMID 38344808, 2024). "Using a pair of paclitaxel-sensitive (PEO1) and -resistant (PEO1-TaxR) ovarian cancer cell line, paclitaxel treatment down-regulated the expression of KIF2C at 48 h and 72 h in PEO1." (PMID 25411964, 2014). "One study reports that KIF2C may be involved in the development of paclitaxel resistance in ovarian cancer." (PMID 34820170, 2021). "In our study, the expression of KIF2C was lower in platinum-resistant ovarian cancer cell lines." (PMID 34820170, 2021). "In contrast, KIF2C expression remained relatively constant in PEO1-TaxR, implicating KIF2C might be involved in the development of paclitaxel resistance in ovarian cancer." (PMID 25411964, 2014). "Furthermore, KIF2C was identified as a novel FOXM1 transcriptional target that might play a pivotal role in mediating paclitaxel resistance in ovarian cancer cells." (PMID 25411964, 2014). "Our further qRT-PCR showed that seven hub genes (BUB1, KIF2C, NUP43, NDC80, NUF2, CCNB2 and CENPN) were differentially expressed in platinum-resistant ovarian cancer cells." (PMID 34820170, 2021). "However, KIF2C expression remained relatively constant in PEO1-TaxR upon paclitaxel treatment, suggesting a role of KIF2C in mediating paclitaxel resistance in ovarian cancer cells." (PMID 25411964, 2014).